CLU (clusterin)
Diseases named in the same sentence as CLU in open-access papers (continued):
Sharing a sentence is not in itself a finding about the gene and the disease.
renal carcinoma (5 papers, 2009 to 2025). A carcinoma arising from the epithelium of the renal parenchyma or the renal pelvis. "The level of clusterin expression in renal cancer cells was found to be closely associated with pathological stage and grade of the tumor, and the overall survival rate of patients with high clusterin expression was obviously lower than that of patients with weak expression." (PMID 26293319, 2015). "The expression level of CLU in renal cancer cells was found to be closely associated with pathological stage and grade of the tumor; and the overall and recurrence-free survival rate of patients with strong CLU expression was significantly lower than that of patients with weak expression." (PMID 22185350, 2011). "It is likely that chemoresistance in RCC is multifactorial, other factors implicated as being involved in the complex chemoresistance mechanisms of RCC include Clusterin; there also is some evidence that lung resistance protein (LRP/MVP) may contribute to inherently resistant renal carcinoma." (PMID 19552816, 2009).
sarcoma (5 papers, 2018 to 2024). A usually aggressive malignant neoplasm of the soft tissue or bone. "The immunophenotype of IPT-like FDC sarcoma is the same as that of FDC sarcoma: positivity for Clusterin CD21, CD23, and CD35, and in addition positivity for EBV." (PMID 34321082, 2021). "FDC may occur in multiple sites and, in addition to FDC markers, Clusterin, a glycoprotein associated with apoptosis, is frequently expressed in FDCS, although not reported in FDC/FRC sarcoma." (PMID 34514557, 2021).
systemic lupus erythematosus (5 papers, 2009 to 2025). An autoimmune multi-organ disease typically associated with vasculopathy and autoantibody production. "It is reported that CLU protein expression decreased in systemic lupus erythematosus patients’ platelets and interacted with thrombotic complications." (PMID 27336623, 2016).
vascular dementia (5 papers, 2016 to 2026). A degenerative vascular disorder affecting the brain. "Despite these subtle associations, the overall impression is, however, that clusterin does not play a major role in atherosclerosis-related diseases like vascular dementia and ischemic vascular disease." (PMID 29534716, 2018). "In the era of the emerging concept of mixed dementia, considering the function of clusterin in neuroinflammation and brain lipid metabolism, clusterin may have a role in the common intersecting pathways of mixed or vascular dementia." (PMID 27861589, 2016). "The mechanism of low clusterin in vascular dementia is inconclusive." (PMID 27861589, 2016). "Plasma Clusterin thus may not be useful in differentiating between Alzheimer and Vascular dementia." (PMID 27861589, 2016).
viral infection (5 papers, 2005 to 2024). "For example, functions of the bottleneck gene CLU are still unclear, but recent transcriptomic and proteomic data demonstrated CLU as a top gene overexpressed by virus infection." (PMID 22312338, 2011). "CTB 2 cells highly expressed CLU, CFD, and IFIT3, suggesting roles in responding to bacterial or viral infection through the innate arm of the immune system." (PMID 35796428, 2022). "Our results demonstrate that genes related to important immune pathways such as antigen presentation, inflammation, apoptosis and response to virus (Cxcl10, CxCl11, Ccl5, Ifr7, Ifi27 Oas1b, Fcerg1,Mif, Clusterin and MHC class II) were upregulated as a result of virus infection." (PMID 18558011, 2008).
Atrophy (4 papers, 2016 to 2023). Any weakening or degeneration, especially through lack of use. "On the other hand, CSO-EPVS remained associated with circulating LDL ApoJ content and corticosubcortical atrophy remained associated with HDL ApoJ, independently of CLU SNPs." (PMID 37113571, 2023). "Previous reports have found clusterin to be associated with measured atrophy in AD-vulnerable brain regions over time, both in participants with MCI and healthy older adults." (PMID 29324756, 2018). "Another study showed increased rates of entorhinal and hippocampal atrophy in individuals with both high CSF clusterin levels and low CSF-Aβ1–42 –a pathologic marker of AD." (PMID 29324756, 2018). "Taken together, these data suggested that CLU deficiency was associated with more cellular infiltrates, especially CD8+ (CD8 T cells) and Mac3+ cells (macrophages), in the kidneys with atrophy." (PMID 27649757, 2016). "Finally, it has been reported that C1q, C3 and clusterin are also associated with higher tTau levels and that clusterin correlates with Aβ-associated atrophy in non-demented elderly." (PMID 36741417, 2022).
depression (4 papers, 2012 to 2024). "Although there are no previous reports linking clusterin to depression, our finding that clusterin is increased in subjects with depression ties in with the growing evidence on inflammatory markers as potential markers for depression." (PMID 23209684, 2012). "A small, but significantly different increase in plasma clusterin was observed in patients with depression when compared to controls, AD, DLB, and FTD subjects (p<0.001)." (PMID 23209684, 2012). "Other confounding factors, such as depression and agitation symptoms, have been reported to increase the plasma clusterin levels, and the plasma amyloid levels may be affected by genetic variants and creatinine levels." (PMID 29169407, 2017). "There was a slight, but significant, increase in plasma clusterin in patients with depression compared to all other groups tested, which may warrant further investigation." (PMID 23209684, 2012). "Although the finding of increased plasma clusterin in depression fits in with the hypothesis of depression being an inflammatory disorder, it is necessary to replicate this finding in a different and larger cohort." (PMID 23209684, 2012). "Interestingly, in the present study, plasma clusterin levels were significantly increased in subjects with depression." (PMID 23209684, 2012). "We examined the correlation between plasma clusterin and MMSE in each group, individually (AD, DLB, PDD, FTD, VaD and depression)." (PMID 23209684, 2012).
endometrial cancer (4 papers, 2020 to 2024). Primary or metastatic malignant neoplasm involving the endometrium (mucous membrane that lines the endometrial cavity). "Six of them were upregulated in endometrial cancer patients (CLU, SERPINC1, ITIH4, C1RL, APOC3 and DSC1), while ten were downregulated (APCS, C9, APOA1, ALB, APOA4, CFHR1, ITIH2, and ACTB)." (PMID 39194522, 2024). "In endometrial cancer patients, the expression of ABCG, ATR, CLU, and LRG1 was upregulated, while the expression of SERPINA1 and KNG1 was downregulated." (PMID 39194522, 2024). "The observation of enhanced levels of clusterin, ITIH4, antithrombin-III, and C1RL in sera of endometrial cancer patients allowed a mathematical model to be built to detect cancer samples." (PMID 36232415, 2022). "Quantification of protein expression revealed the upregulation of CLU, ITIH4, SERPINC1, and C1RL in endometrial cancer samples compared to the sera of control subjects." (PMID 34298850, 2021). "Several blood-based protein biomarker candidates for endometrial cancer detection were suggested, including the Apolipoprotein family (APOA1/4, APOC1/2/3, and APOE), Clusterin (CLU), Inter-alpha-trypsin inhibitor heavy chain (ITIH2 and ITIH4), and Antithrombin III (ATR/SERPINC1)." (PMID 39194522, 2024). "Further investigations into differentially expressed proteins in non-malignant and type I and II endometrial cancer samples using iTRAQ identified 1387 proteins, with 3 novel candidates suggested: WFDC2, CLU, and MUC5B." (PMID 39194522, 2024).
frontotemporal dementia (4 papers, 2012 to 2022). Frontotemporal dementia (FTD) comprises a group of neurodegenerative disorders, characterized by progressive changes in behavior, executive dysfunction and language impairment, as a result of degeneration of the medial prefrontal and frontoinsular cortices. "We next evaluated the expression pattern of CLU isoforms in the hippocampus and cortex of Tg4510 mice overexpressing the human mutant P301L Tau associated with frontotemporal dementia." (PMID 25051234, 2014). "They demonstrated an elevation in clusterin in frontotemporal dementia (FTD), PSP, and CBD—NDDs with dominant tau or TAR DNA-binding protein (TDP)-43 proteinopathy but minimal α-synuclein pathology—as compared to healthy individuals." (PMID 35326174, 2022).
Hyperglycemia (4 papers, 2014 to 2023). An increased concentration of glucose in the blood. "Taken together, these data suggest that oxidative stress, but not hyperglycemia or the renin-angiotensin system, is the principal factor underlying the upregulation of clusterin expression in podocytes under diabetic conditions." (PMID 32913257, 2020).
hyperlipidemia (4 papers, 2019 to 2021). "Importantly, A2M, APP, CLU, IGF2 and PLAU are not among the hyperlipidemia associated genes, they are retrieved only after obtaining the disease module with DIAMOND." (PMID 34824199, 2021).
myocardial ischemia (4 papers, 2020 to 2025). A disorder of cardiac function caused by insufficient blood flow to the muscle tissue of the heart. "Even though we provide evidence that plasma clusterin levels are regulated during controlled myocardial ischemia, several limitations to our study should be mentioned." (PMID 32605184, 2020). "In the early and later stage of myocardial ischemia, plasma clusterin levels are found to be both increased and decreased." (PMID 32605184, 2020). "Elevated plasma clusterin levels 120 min after AMI onset suggest that clusterin might be an additional early biomarker of myocardial ischemia." (PMID 32605184, 2020).
nasopharyngeal carcinoma (4 papers, 2008 to 2024). A carcinoma arising from the nasopharyngeal epithelium. "In nasopharyngeal carcinoma, N,N′-dinitrosopiperaxine (DNP), a carcinogenic factor, upregulates CLU, thereby inducing MMP-9 and VEGF expression, which promote metastasis." (PMID 37685987, 2023).
oral cancer (4 papers, 2022 to 2025). "CLU has been reported to have tumor suppressor activity in prostate, lung, and oral cancers, and low expression of CLU is associated with worse prognosis and genetic instability." (PMID 36685863, 2022). "Similarly, the gain and loss of function of CLU also altered OCR levels in oral cancer cells during cisplatin treatment." (PMID 38447939, 2024). "However, CLU knockdown caused a significant increase in the mt-DNA level irrespective of cisplatin treatment, confirming that CLU is involved in inducing mitophagy in oral cancer cells." (PMID 38447939, 2024). "In oral cancer cells, CLU overexpression enhances the activation of the AMPK/Akt/mTOR-mediated autophagy pathway, hence promoting cell survival." (PMID 40475773, 2025). "More importantly, CLU KD enhanced cisplatin-induced cytotoxicity as indicated by lower cell viability, which was reversed in CLU-overexpressing oral cancer cells during cisplatin treatment." (PMID 38447939, 2024). "Here, we showed that CLU (clusterin) is localized to mitochondria to induce mitophagy controlling mitochondrial damage in oral cancer cells." (PMID 38447939, 2024). "Collectively, our results suggest that inhibition of CLU-mediated mitophagy flux could function as a novel mechanism to potentiate cisplatin treatment in oral cancer cells." (PMID 38447939, 2024). "In fact, CLU has been reported to exhibit tumor suppressor activity in lung and oral cancers." (PMID 37239129, 2023). "In a recent investigation on oral cancer stem cells, it was discovered that treating the cells with cisplatin promoted the activation of mitophagy—a mechanism for the elimination and prevention of damaged mitochondria accumulation to avoid cell death—by regulating the levels of CLU." (PMID 37239129, 2023). "Our study showed that CLU and PPARGC1A coordinately regulate mitophagy and biogenesis to enhance cell survival in oral cancer during cisplatin treatment." (PMID 38447939, 2024). "To establish the correlation between CLU and PPARGC1A in regulating mitochondrial functionality, we measured the alteration in their expression in oral cancer cells." (PMID 38447939, 2024). "In conclusion, CLU and PPARGC1A are essential for sustained cancer cell growth by activating mitophagy and mitochondrial biogenesis, respectively, and their inhibition could provide better therapeutic benefits against oral cancer." (PMID 38447939, 2024). "We suggest that CLU and PPARGC1A are indispensable for controlling mitochondrial content during chemotherapeutic stress and that modulating their activity could strongly influence therapeutic responses in oral cancer." (PMID 38447939, 2024). "Intriguingly, we noticed that CLU interacts with both LC3 and BAX, presumably forming a trimeric complex (BAX-CLU-LC3) in cisplatin-treated cells recruiting a phagophore to generate a mitophagosome around damaged mitochondria for successful mitophagy leading to enhanced oral cancer cell survival." (PMID 38447939, 2024).
osteosarcoma (4 papers, 2006 to 2025). A usually aggressive malignant bone-forming mesenchymal neoplasm, predominantly affecting adolescents and young adults. "Conversely, CLU knockdown sensitizes osteosarcoma cells to cisplatin, suggesting its dual role as a stress-responsive cytoprotectant and metastasis promoter." (PMID 40606578, 2025). "CLU protein levels also increased in a dose-dependent manner after ZOL treatment in all tested osteosarcoma cell lines, as analyzed by western-blotting." (PMID 25138053, 2014). "First we assessed the effects of ZOL treatment on CLU expression in vivo in HOS-MNNG osteosarcoma xenografts using immunohistochemistry." (PMID 25138053, 2014). "In human osteosarcoma cells, CLU overexpression correlates with therapeutic resistance." (PMID 40606578, 2025). "CLU expression is rapidly up-regulated in various cancer tissues, including osteosarcoma." (PMID 25138053, 2014). "Based on these data, knockdown of CLU using OGX-011 could potentiate the effect of zoledronic acid in osteosarcoma treatment." (PMID 25138053, 2014). "Several studies have shown that secreted clusterin (sCLU) up-regulation inmulti-drug resistant osteosarcoma (OS) cells relates to enhanced drug resistance.Furthermore, sCLU silencing directed against sCLU induces significant reduction ofcellular growth and sensitizes OS cells to chemotherapy." (PMID 25106434, 2014). "In human OS, CLU levels are overexpressed in OS to a variable extent, especially after conventional therapy and could be a valuable marker of aggressive extraosseous osteosarcoma." (PMID 25138053, 2014). "Confirming the idea that CLU confers resistance to ZOL, we then transiently overexpressed CLU in osteosarcoma cells." (PMID 25138053, 2014). "We hypothesized that targeting CLU using siRNA or the antisense drug, OGX-011, will suppress treatment-induced CLU induction and enhance ZOL-induced cell death in osteosarcoma (OS) cells." (PMID 25138053, 2014). "As CLU is overexpressed after ZOL treatment and is known to confer resistance to treatment in various cancers, we hypothesized that CLU could be involved in the emergence and maintenance of resistance of osteosarcoma cells to ZOL treatment." (PMID 25138053, 2014).
pulmonary fibrosis (4 papers, 2017 to 2025). Chronic progressive interstitial lung disorder characterized by the replacement of the lung tissue by connective tissue, leading to progressive dyspnea, respiratory failure, or right heart failure. "Our integrative analysis reveals novel molecular connections between cellular senescence programs and fibrotic lung remodeling, positioning CLU and LCN2 as pivotal regulators of age-associated pulmonary fibrosis." (PMID 41562054, 2025). "In contrast, we find an enrichment of several markers of pulmonary fibrosis (CLU, COL1A1, COL1A2, and COL3A1) in SARS-CoV-2-low patients (these correspond to the later stages of infection), indicating that there are two distinct stages of infection." (PMID 35233546, 2022). "Clusterin, an extracellular chaperone and regulator of cell functions, is reduced in bronchoalveolar lavage fluid of patients with pulmonary fibrosis." (PMID 29382921, 2018). "We hypothesize that through targeted modulation of LCN2 and CLU, these agents may attenuate pulmonary fibrosis progression, suggesting a novel therapeutic strategy for IPF." (PMID 41562054, 2025). "Herein, we characterized the role of Clusterin in clinical and experimental pulmonary fibrosis." (PMID 29133960, 2017). "Exogenous supplementation of Clusterin to wildtype mice in this model did not modulate apoptosis, lung fibrosis or the burden of double strand DNA breaks or oxidative DNA damage." (PMID 29133960, 2017). "However, the localization of clusterin in normal and fibrotic lung, the mechanisms contributing to its down-regulation in IPF BALF and its role in the pathogenesis of pulmonary fibrosis have not been investigated." (PMID 29382921, 2018).
age-related macular degeneration (3 papers, 2021 to 2023). Age-related loss of vision in the central portion of the retina (macula), secondary to retinal degeneration. "In the eye, CLU expression has been reported as being severely increased in several pathologies, such as age-related macular degeneration and Fuch’s corneal dystrophy, while it is depleted in others, such as pathologic keratinization." (PMID 37685987, 2023). "A comparative tear proteomic study of 30 RVO patients with age-related macular degeneration demonstrated proteome enrichment by complement factors (C3 and C9), clusterin (CLU), S100A9, and S100A8 proteins." (PMID 36498980, 2022).
anaplastic large cell lymphoma (3 papers, 2006 to 2025). Anaplastic large cell lymphoma (ALCL) is a rare and aggressive peripheral T-cell non-Hodgkin lymphoma, belonging to the group of CD30-positive lymphoproliferative disorders, which affects lymph nodes and extranodal sites. "In humans, clusterin expression was specific to anaplastic large-cell lymphoma and provided an additional diagnostic marker." (PMID 35765478, 2022). "Virtually all (82–100%) systemic anaplastic large-cell lymphomas, including ALK+ and ALK– cases, and 41–100% of PC anaplastic large-cell lymphomas express clusterin, a ubiquitous glycoprotein encoded by a gene on chromosome 8p21." (PMID 16623775, 2006). "Although well-differentiated neuroendocrine tumors strongly express CLU at many anatomical sites, other tumor types, such as anaplastic large-cell lymphoma, follicular dendritic cell sarcoma, and tenosynovial giant cell tumors, have also expressed CLU." (PMID 39937015, 2025).
cholestasis (3 papers, 2019 to 2025). Impairment of the bile flow caused by obstruction within the liver, or outside the liver in the bile duct system. "Regardless of its primary action as a chaperon protein responsible for ECM homeostasis, it has been hypothesized that CLU may inhibit precipitation of biliary proteins, possibly resulting in an imbalance between synthesis and degradation of bile acid implicated in progressive cholestasis." (PMID 33184463, 2020).
diffuse large B-cell lymphoma (3 papers, 2018 to 2022). "The extracellular chaperone clusterin is highly expressed in systemic ALCL, showing a characteristic Golgi staining pattern; however, clusterin reactivity has also been shown in a subset of diffuse large B-cell lymphomas (DLBCL), and in cases of PTCL-NOS and CHL." (PMID 29617304, 2018).